IL10 (interleukin 10)
Diseases named in the same sentence as IL10 in open-access papers (continued):
Sharing a sentence is not in itself a finding about the gene and the disease.
infection (continued). "When cells were treated with UV-inactivated TCRV almost no release of IL-6 or IL-10 was detected, in contrast to infection with infectious TCRV." (PMID 21572983, 2011). "Previous to the infection, analyzing the mononuclear cells isolated from Peyer's patches, it was observed that mice fed 7 days with L. casei CRL 431 significantly increased cytokines expression and also the release of IFNγ and IL-10 by these cells." (PMID 21813005, 2011). "Albeit IL-10 mRNA expression increased in the ears of animals infected with the LTCP393(R) isolate at seven weeks post infection, it was not significantly different from that detected in the ears of LTCP15171(S)-inoculated mice." (PMID 21390155, 2011). "Nevertheless, it has also been reported that different strains may induce different IL-10 responses in PBMC and, therefore, different outcomes of the infection and the resulting immune response could be expected after infection with different strains." (PMID 21314968, 2011). "To determine whether IL-10 was critical for IVIG mediated protection against HSV induced CNS inflammation, we compared the outcome of infection in 129 WT and IL-10 KO mice treated with either IVIG or PBS at 24 h pi." (PMID 21655109, 2011). "By day 7 post i.v. infection, IL-10 mRNA was detected in bronchial lavage cells but not lymph nodes (LNs) or peripheral blood mononuclear cells while IFNγ mRNA was detected later." (PMID 21852945, 2011). "Among the different cytokines analyzed in our study, the sera levels of IL-6 and IL-10 were considerably higher in the P(H1N1) patients than that of the non-ILIs infection patients and the healthy controls." (PMID 22174866, 2011). "Seven days after infection, the cells isolated from S and Lc-S groups showed similar releases of IL-10, without significant differences compared to healthy mice (C and Lc groups)." (PMID 21813005, 2011). "At day 14 of infection, strains of the East Asian/Beijing lineage induced significantly higher concentrations of IL-12p40 and interferon-γ in BAL, and lower concentrations of IL-10, than strains of the other lineages." (PMID 21931620, 2011). "As report in this work, high levels of serum IL-10 could be detected in the sera of GBS infected newborn mice early (1 h and 4 h) upon infection." (PMID 22114550, 2011). "Although il12p40, il4, and il10 levels after immunization were increased compared with post-infection, the differences were not significant." (PMID 20976218, 2010). "Plasma cytokine levels were either not different between the groups (TNF-α, IL-6, IFN-γ) or below detection (MCP-1, IL-12, IL-10) at both 24 and 48 hours after infection (data not shown)." (PMID 20682036, 2010). "Since IL-2Jc treatment increased IL-10 and CTLA-4 expression by Foxp3+ CD4+ T cells during infection, we hypothesized that protection was dependent upon these two molecules." (PMID 21170302, 2010). "In egg-negative people IL-10 levels followed the age-infection profile while IL-5 levels lagged behind, only beginning to rise when infection levels peaked." (PMID 21039611, 2010). "At day 30 after infection, the spleen cells from castrated males that were reconstituted with estradiol responded to the paracoccin stimulus by producing more IFN-γ and less IL-10, reproducing the pattern of cytokines released by cells of the intact females, under similar experimental conditions." (PMID 20505765, 2010). "In contrast to observations in macrophages at 24 h p.i., infection of DCs with WNV alone resulted in a small increase in IL-10 mRNA levels, although this difference was not significant (p = 0.09)." (PMID 20661470, 2010). "In addition, the induction of the cytokines IL6, IL10, and the chemokine CCL2 occurred during acute infection." (PMID 20019816, 2009). "The levels of sTNF-RII (P = 0·004), IL-10 (P = 0·018) and IL-5 (P = 0·043) were significant for comparisons between children with neither, one or other single infection or co-infected children." (PMID 19149774, 2009).
infection (continued). "No significant increases in IL-10 gene expression were observed in response to WT or ΔPT through day 2 post-infection." (PMID 19759900, 2009). "Infection with HIV induces immune activation with high levels of circulating cytokines, such as tumor necrosis factor-alpha (TNF-α), interleukin-6 (IL-6), IL-10, and some chemokines." (PMID 19852800, 2009). "With progressive infection, levels of IFN-γ and IL-12 remained low although pronounced stimulation of IL-4 and IL-10 (p<0.001) compared to the level before infection, were observed in the supernatants from splenocytes of control infected mice stimulated with different antigens." (PMID 19503834, 2009). "Studies on infections of bacteria, protozoa and some viruses suggest that expression of IFN-γ is up-regulated and participates in controlling infection in the absence of IL-10 signaling." (PMID 19816558, 2009). "IL-10 mRNA has been previously measured in the draining lymph node of healer and nonhealer mice following infection with L. major parasites." (PMID 19292771, 2009). "Prolonged infection was not due to IL-10-mediated immunosuppression, and PRRSV did not elicit a specific IFN γ response, especially in non-adult animals." (PMID 19860914, 2009). "Infection of macrophages with the protozoan parasite Toxoplasma gondii results in inhibition of a large panel of LPS-responsive cytokines, including TNF-α, while leaving others such as IL-10 intact." (PMID 19859561, 2009). "We also detected an increase in IL-10 gene expression near the peak of infection with WT, but not ΔPT, indicating induction of a complex mixture of T cell subtypes during this infection." (PMID 19759900, 2009). "Therefore, increased expression of Tlr2, leading to increased levels of IL-10 and increased survival of regulatory T cells, may dampen the immune response against C. albicans, even in the presence of immune infiltrates in the kidney, and allow infection to progress." (PMID 19845042, 2009). "To further assess whether type I IFN plays an antiviral role in macrophages from IL-10−/− mice, we incubated macrophages with anti-IFN-α/β receptor neutralizing mAb and measured viral replication by Q-PCR after infection with WNV (MOI = 1)." (PMID 19816558, 2009). "Treatment with L. casei enhanced the levels of IL-10 in BAL and in serum prior to infection." (PMID 19835595, 2009). "Before infection there was no stimulation of IL-10 production in any of the vaccinated groups in response to antigens." (PMID 19503834, 2009). "Unlike the case of IL-10, infection with T. gondii inhibited TNF-α production during LPS and LPS + IC stimulation to background levels." (PMID 19859561, 2009). "The BALF samples did not contain detectable levels of TNF-α and IL-10, independent of infection time." (PMID 19383119, 2009). "In contrast to the proinflammatory cytokines, the antral IL-10 mRNA level of WT-infected gerbils was not significantly induced after 4 weeks of infection, but constantly increased up to 15-fold after several months of infection." (PMID 19270747, 2009). "In this study, we found persistently high serum concentrations of IL-6 and IL-10 in patients with severe AP and in patients who developed infection, but not in patients with mild AP or uninfected patients." (PMID 19442309, 2009). "Therefore, the amount of IL-10 being produced in co-cultures of T cells and MoDCs isolated ex vivo from FMDV infected swine at different times post-infection was evaluated." (PMID 19478852, 2009). "Since the inflammatory response might explain the rapid signs of illness in VVΔE3L infected ISG15 KO mice, we measured serum cytokine levels (IL-6, TNF-α, IL-10, MCP-1, IFN-γ, and IL-12 p 70) at early times post infection." (PMID 18604270, 2008). "Interestingly the frequencies and numbers of IL-10+ CD4+TCR-β+ cells were equivalent in PyL and PyNL infected mice on day 7 post-infection." (PMID 18401464, 2008).
infection (continued). "The cytokines are divided into two important groups: theproinflammatory such as IL-1, IL-6, and TNF-α, and the anti-inflammatory such as IL-10,and have a negative impact on resistance to infection and in septic mice,reduction of IL-10 levels improves survival." (PMID 18604304, 2008). "In addition, M2 protein expression correlates with high serum IL-10 levels and an increased frequency of virus-specific CD8+ T cells during MHV68 infection." (PMID 18389062, 2008). "Although IL10 mRNA did not appreciably increase at 3d of infection, we observed a significant increase in levels of IL-10 in culture supernatants after 3 days of co-cultivation." (PMID 18575603, 2008). "Overall, the immune response in the absence of M2 protein expression during infection is unique in that the MHV68-specific T cell response is increased correlating with a decrease in serum IL-10 levels." (PMID 18389062, 2008). "The involvement of a Treg-like subset, as implied by the up-regulation of TGF-β and IL-10 at 33 dpi, was not seen in the chronic phase of SL infection." (PMID 18945374, 2008). "Within the testis, the levels of expression of the immunosuppressive cytokines IL-10 and TGFβ and pro-inflammatory cytokines IFNγ, IL-1β, TNFα transcripts was not significantly changed following infection." (PMID 18347738, 2008). "Expression of IL-10 mRNA was determined by real time PCR in purified splenic CD4+ T cells obtained on days 1, 3, 5 and 7 post-infection from wild type (WT) C57/BL6 mice and plasma levels of IL-10 were determined by ELISA on days 1, 3, 5 and 7 pi from WT and RAG−/− mice." (PMID 18401464, 2008). "Important roles have been demonstrated for both IL-10 and TGF-β in modulating the outcome of murine malaria infections, and observational data strongly suggests that they play a similar role in human infections." (PMID 18401464, 2008). "At no point during either PyL or PyNL infection did we observe significant IL-10 production by myeloid (CD11b+), lymphoid dendritic cells (CD11c+) or macrophages (F4-80+) (results not shown)." (PMID 18401464, 2008). "In order to study the extent and kinetics of the inflammatory response, we sacrificed WT, TLR2 KO, and TLR4 KO mice at multiple time points after infection and measured the concentrations of the proinflammatory cytokines TNFα and IL6 and the anti-inflammatory cytokine IL10 in lung homogenates." (PMID 17676990, 2007). "Transcripts for several other cytokines (IL-2, IL-4, IL-10, and IL-12) were detected on the array, but their levels did not change significantly during the course of infection." (PMID 17725815, 2007). "In addition, lung IL10 concentrations were moderately lower in TLR2 KO mice at 24 and 48 h after infection (p < 0.05)." (PMID 17676990, 2007). "A potential criticism of the antibody-mediated IL-10 neutralization studies is that IL-10 was not blocked throughout the course of the virus-infection." (PMID 17570849, 2007). "To distinguish between these two possibilities we compared the anti-LCMV antibody responses at day 8 post-infection in groups of LCMVClone13-infected mice with or without anti-IL-10 treatment." (PMID 17570849, 2007). "T cells from mice treated with anti-IL-10 late in the infection were non-functional and indistinguishable from untreated LCMVClone13-infected mice (data not shown)." (PMID 17570849, 2007). "LCMV-specific IgG levels in the IL-10-blocked, persistently infected mice were not significantly different than untreated controls at day 8 post infection (p = 0.2)." (PMID 17570849, 2007). "Interestingly, we observed that in vitro infection with H37Rv induced the whole blood cultures from HIV patients to synthesize increased levels of cytokines such as IL-1, TNF-α, IL-6 and IL-10." (PMID 16504020, 2006). "Comparisons of infections with a type strain of MAP and M. avium avium in bovine MDMs have revealed an increased expression of TNFα in cells infected with M. avium avium and a down regulation of IL-10." (PMID 16478544, 2006).
infection (continued). "IL-6 and IL-10 secretion was not altered by TLR7/8 stimulation prior to infection." (PMID 41974867, 2026). "LTA -+252 and CCC, TNFA-308 and CCC, IL10-819 rs1800871 and CCC, TLR4 haplotype D229G/T399I with protection from CCC, TIRAP S180L (rs8177374) and rs8177376 (strong linkage disequilibrium) with CCC, IL18 rs360719 and infection, IL17A rs4711998 and infection, TGFB1+10 rs1800470 with infection." (PMID 40297326, 2025). "According to previous evidence, both adjuvants—ISPA and Quil-A—support IL-10 production and secretion of IFN-γ, which would contribute to a balanced and regulated immune response, crucial for both effective immunity and the prevention of immune-related damage in infections like T. cruzi." (PMID 41007442, 2025). "Although the infection increased IL-10 production, the treatments did not alter its levels." (PMID 40142455, 2025). "Somewhat surprisingly, the production of IL-10 and IFN-γ was much higher in mice infected with wild-type K7 and received IFA treatment, indicating that IFA treatment facilitated the development of an inflammation-controlling and infection-limiting response to fight against K. pneumoniae in mice." (PMID 39761301, 2025). "Under limited bacterial challenge conditions (3:1 MOI), CAY10404 preconditioning caused statistically detectable IL-10 suppression relative to SA113 monotherapy (p < 0.05); however, this inhibitory effect was not significant (p > 0.05) when the infection intensity was increased to 10:1 MOI." (PMID 40867507, 2025). "In addition, mangiferin was found to modulate host immune responses by simultaneously inhibiting pro-inflammatory cytokines, IL-6 and TNF-α, and upregulating the expression of anti-inflammatory IL-10 and antiviral IFN-γ, thus mitigating infection-induced inflammation." (PMID 40733492, 2025). "However, we routinely noted an increase in serum IL-6 and IL-10 in both the A/J and WT B6 mice at peak infection with the Ig::Tn NMII strain, which could potentially be related to infection of adipocytes." (PMID 40586810, 2025). "Furthermore, after infection and the addition of a PKA activator, the expression levels of p-CREB (P < 0.05), C/EBPβ (P < 0.05), Arg-1 (P < 0.01), and IL-10 (P < 0.05) were significantly upregulated in human dMφ compared with those of the group infected with T. gondii alone." (PMID 39994736, 2025). "However, in vivo infection of IL-10−/− mice showed no antimicrobial activity of benzoic acid alone, and only in combination with butyric, caprylic and sorbic acids C. jejuni loads were reduced in the duodenum, but not in the stomach, ileum or colon." (PMID 40395728, 2025). "It was reported that the stimulation of macrophages with LPS or the infection with Gram-negative pathogens not only induces changes in their expression and production of inflammatory factors but in addition, modulate regulatory factors like IL-10 and IL-27." (PMID 40141330, 2025). "We next investigated whether the improved survival observed in mice lacking B cell-derived IL-10 resulted from a better ability to control bacterial loads after HN878 infection." (PMID 40260245, 2025). "Il22−/− mice, with or without FT, displayed induction of IL-17A, IL-17F, and IL-10 upon infection." (PMID 41361166, 2025). "The study concluded TNF-α lacked specificity for bacterial etiology and could not discriminate infection severity, reinforcing its limited clinical utility compared to IL-6/IL-10." (PMID 40647525, 2025). "BR15 infection induced a modest but statistically significant increase in TNF-α expression (p < 0.05) and a significantly higher expression of IFN-β1, IL-1β, IL-6, and IL-10, as well as the chemokines CCL2 (MCP-1), CCL5 (RANTES), and CXCL8 (IL-8), compared to MR766-infected cells." (PMID 40732762, 2025).
infection (continued). "Infection with MHV-68 resulted in an elevated abundance of cytokines (TNF-α and IL-6) that triggered inflammation, an upsurge in pyroptosis-related molecules involving caspase-1, IL-1β, and IL-18, along with a decrease in IL-10 concentration, an anti-inflammatory cytokine, in peritoneal macrophages." (PMID 40041420, 2025). "Additionally, severe influenza virus infection was associated with hypercytokinemia, including increased cytokine (IFNβ, TNF, IL-10 and IL-12p70) and chemokine (MCP-1 (CCL2), KC (CXCL1), IP-10 (CXCL10) and RANTES (CCL5)) levels in the severe infection group at 7 dpi." (PMID 41285788, 2025). "Similarly, IL-10–producing CD19+ B1 cells were significantly diminished in all treated groups compared with infected controls (p < 0.001), suggesting suppression of infection-induced Breg responses." (PMID 40725240, 2025). "One study showed a decrease in M-MDSCs after KPPR1 infection, while another reported that early recruitment of M-MDSCs to the lungs during CR-Kp (ST258, KP35) infection promoted bacterial clearance, protected lung tissue, and improved host survival through IL-10 production." (PMID 40096073, 2025). "Deferoxamine prophylactically given to microbiota-depleted IL-10−/− mice 7 days prior C. jejuni infection did not affect bacterial loads in the mice intestine, but significantly improved the clinical outcome of infected mice at day six post-infection." (PMID 40395728, 2025). "However, at 24 h post-infection, the expression levels of TNF-α, IL-1β, and IL-6 were markedly reduced, while the secretion of the chemokine IL-8 continued to increase, and the anti-inflammatory cytokine IL-10 was significantly upregulated (P < 0.05)." (PMID 40874199, 2025). "However, since infection with male worms only (without egg production) also promotes IL‐10 producing B cells, we here studied the stimulatory effects of adult worm ES and EVs on murine and human B cells." (PMID 40916477, 2025). "Intriguingly, infections with male worms only, and thus in the absence of eggs, could still protect mice against experimental anaphylaxis in a B cell‐ and IL‐10‐dependent manner." (PMID 40916477, 2025). "Increased CSF IL-10 level (cutoff values including: ≥0.43 pg/mL, ≥2 pg/mL, ≥4 pg/mL, ≥8.2 pg/mL, ≥8.3 pg/mL, ≥10.13 pg/mL, and ≥16.15 pg/mL) indicated poor PFS, facilitated discriminating PCNSL from systemic NHL and other CNS diseases (infection/inflammation, or other malignant tumors in CNS)." (PMID 40881684, 2025). "Mice lacking IL-10 showed resistance to infection when conidia were administered intravenously." (PMID 38667922, 2024). "As opposed to this, the plasmatic concentration of IL-10 was not affected by the disease status, consistent with the view that this cytokine is synthesized and secreted locally (at sites of infection), as proposed for PTX3." (PMID 38790226, 2024). "IL-10 plays a multifaceted role in host protection and indirectly promotes humoral immunity by modulating B cell function; however, the role of IL-10 during infection with Anaplasmataceae family pathogens is not well elucidated." (PMID 39770719, 2024). "Notable contributions include the importance of IL-10 in infection outcome, something that was not predicted by mouse models, and the complex, dynamic balance of pro- and anti-inflammatory signals necessary to contain infection and limit pathology." (PMID 38517920, 2024). "Although CAF01 is a highly promising adjuvant that overcomes IL-10 mediated suppression, it is notable that correlates of immunity in humans have been less clearly defined, and IFN-γ appears to be the crucial factor in macrophage-mediated control of infection humans." (PMID 39681568, 2024). "However, IL10 secretion was induced at much lower bacterial loads as compared to IL6, indicating potential skewing towards a more anti-inflammatory response, which is consistent with the prevalent asymptomatic nature of the infection." (PMID 38808065, 2024).